STAT1 (signal transducer and activator of transcription 1)
Diseases named in the same sentence as STAT1 in open-access papers (continued):
Sharing a sentence is not in itself a finding about the gene and the disease.
infection (continued). "(H) HeLa 229 cells were either left untreated or were pre-treated for 2 hr with 10 ng/mL of IFN-γ and infected with Chlamydia (Ctr) at MOI 1 and lysed at 30 hpi to study STAT1 signalling after Ctr infection (n=3)." (PMID 36155135, 2022). "Our latest study also showed that insulin downregulated the infection of bladder epithelial cells caused by UPEC in a high-glucose environment, and its regulation was also obviously regulated by the JAK/STAT1 signaling pathway." (PMID 35563546, 2022). "This is also a mechanism used by the mumps virus (MuV) to block IFN pathways, as demonstrated by the ability of this virus to reduce constitutive STAT1 levels 10 h after infection." (PMID 35456913, 2022). "To further investigate the role of STAT1 during tissue injury response, we analyzed mice 10 days post infection." (PMID 34497340, 2022). "In order be an acceptable surrogate model, we expected that ML29 infection of STAT1-/- mice would generate comparable results." (PMID 36289695, 2022). "Pull-down of TAP-tagged 018 expressed from vTAP-018 confirmed the 018:STAT1 interaction during infection." (PMID 35182467, 2022). "Villin Cre STAT1 floxed mice exhibit infections on the order of Ifng-/- mice due to the inability of the enterocyte to respond to IFNγ." (PMID 35584177, 2022). "In STEC O113 ΔsubAB-infected cells, STAT1 phosphorylation markedly increased at 6 h after infection." (PMID 35345462, 2022). "Stat1-/- mice phenocopy Ifng-/- mice, succumbing to T. gondii infection during the acute stage of infection." (PMID 36067217, 2022). "We observed that infection with RSV or IAV leads to the robust activation (phosphorylation) of STAT1 and STAT2 in A549 WT cells as well as IFNLR1 KO cells." (PMID 36326278, 2022). "We also observed an increase in total STAT1 protein at 24 hours post infection indicating that STAT1 itself was induced by the infection, in line with its classification as an ISG." (PMID 35584177, 2022). "In conclusion, our findings here demonstrate that both CD4 and CD8 T cells play a role in acute pathogenesis during ML29 infection in STAT1-/- mice; 100% survival is only achieved with a double CD4 and CD8 T cell depletion." (PMID 36289695, 2022). "The human cytomegalovirus (HCMV) has developed mechanisms that can counteract the control of infection by inhibiting the phosphorylation of tyrosine 701 of STAT1." (PMID 35456913, 2022). "The transcriptional changes upon infection were dominated by Ifng and its downstream genes (e.g. Stat1, Irf1, Fcgr1, Nos2, Cxcr3) and IFN-dependent CXCR3 binding chemokines (e.g. Cxcl9, Cxcl10)." (PMID 36400767, 2022). "As found in previous studies, probing whole-cell lysates by western blot showed that following VSVΔ51 infection, vanadate increases phosphorylation of STAT1 and decreases phosphorylation of STAT2." (PMID 35572196, 2022). "From our first round of infections, of the three Stat1-/- mice in which infection was allowed to proceed past 3 dpi, one mouse died at 4 dpi, another at 7 dpi, and the third survived until euthanized at 30 dpi." (PMID 33705489, 2021). "The principal effect of YTHDF3 depletion on the innate host response to PVSRIPO infection was dampened induction of ISGs (STAT1, MDA5, IFIT1, ISG15, OAS1)." (PMID 33849973, 2021). "Homozygous or compound heterozygous mutations of STAT1 lead to complete or partial STAT1 LOF, which is associated with susceptibility to infection by intracellular pathogens and herpetic infections." (PMID 33777053, 2021). "On the other hand, we also found that infection with both strains results in caspase-3-dependent STAT1 cleavage." (PMID 34512601, 2021). "Accordingly, A375 and T3M4 cells responded with vigorous innate immune responses to PVSRIPO (MOI 10) infection, evident by abundant p-STAT1(Y701) induction." (PMID 33849973, 2021). "Brains from these mice were harvested and homogenized, and homogenate from each mouse was separately inoculated IC into naive Stat1-/- mice in parallel for a second round of infection." (PMID 33705489, 2021).
infection (continued). "Consistently, we found higher viral loads in the small intestines upon rSA11 infection than upon rSA11-NSP1-null infection of Stat1 KO mice." (PMID 34903043, 2021). "Herein, we show that the infection of HCC-derived Huh7.5 cells with HCV promotes upregulation of the protein inhibitor of activated STAT1 (PIAS1)." (PMID 34684276, 2021). "To determine the mechanisms by which STAT1 and STAT2 levels decrease during infection, we then quantified the amount of STAT1 and STAT2 mRNA in mock infected and ASFV infected PAMs." (PMID 34512601, 2021). "Specifically, a 80 kDa faster migrating form of STAT1, which differs from the STAT1β isoform (84 kDa), was detected by Western blot during infection with NH/P68 and Arm/07/CBM/c2." (PMID 34512601, 2021). "Several restriction factors (IRF1, MX1, STAT1, C18orf25) known to limit lytic infection were expressed at lower levels in the lytic subcluster." (PMID 33914843, 2021). "The observed STAT1 upregulation in IND patients supports previous studies that report the activation of STAT1 signaling pathway in host cells after infection with T. cruzi leading to a significantly elevated STAT1 expression." (PMID 34552885, 2021). "In response to H1N1 or H3N2, there was increased expression of Il-15, Tlr3, and Stat1 detected in young lung at day 7 of infection." (PMID 34829979, 2021). "After STM infection migratory ILCs express significantly higher levels of Ccl3, Gbp2, Gbp6, Irf1, Irf4, Irf7, Pml and Stat1, all of which are regulated in response to interferon gamma." (PMID 33414524, 2021). "In conjunction with epithelial IFN production in response to RV, there are other antiviral mechanisms that appear to be dysregulated during infection, such as the signal transducer and activator of transcription 1 (STAT1) signalling pathway." (PMID 34912343, 2021). "Examination of CR6-infected Stat1-/- mice at 21 dpi revealed convergence of tissue viral levels to those found in the rare mice surviving CR6F514I infection." (PMID 33705489, 2021). "At day 3 post infection there was an increase in Ifnα2, Isg15, and Stat1 gene expression detected in young adult lung in response to either H1N1 or H3N2." (PMID 34829979, 2021). "This impaired ability of type I IFN to restrict infection has been demonstrated to be dependent on the viral antagonism of IFN-mediated phosphorylation of STAT1 and STAT2." (PMID 34338586, 2021). "PECs from STAT1+/+ mice recruited acutely during infection with this helminth significantly inhibited the proliferative response of both CD4+ and CD8+ splenocytes, reducing this response by at least 50%." (PMID 34684235, 2021). "We have not directly measured arginase in BM iMO in this study, but iNOS production was clearly elevated throughout the course of infection through a IFNγ-dependent pathway, most likely involving STAT1 signaling." (PMID 34557190, 2021). "The p‐JAK2/JAK2 and p‐STAT1/STAT1 ratio reached highest level at 10 days post‐infection and decreased at 20 days post‐infection." (PMID 33959966, 2021). "STAT1 mediated the recruitment of inflammatory monocytes and the development of alternatively activated macrophages (M2) at the site of infection." (PMID 34684235, 2021). "Because IFN-γ–induced STAT1 is important in control of T. gondii, it is counterintuitive that infection of cells alone is sufficient to induce STAT1 phosphorylation, nuclear translocation, and association with host DNA." (PMID 34670268, 2021). "Both SARS-CoV and SARS-CoV-2 have been demonstrated to block nuclear import of the transcription factor, STAT1, during infection in cell culture." (PMID 33849972, 2021). "STAT1 was strongly degraded during the infection with Arm/07/CBM/c2 at 16 hpi (91 kDa band), while this degradation was less evident with the attenuated isolate NH/P68." (PMID 34512601, 2021).
infection (continued). "All the TW2015-infected Stat1-/- mice showed severe weight loss and died within one week post-infection, but the NGC- and D2Y98P-infected Stat1-/- mice had 0% and 25% mortality rates, respectively." (PMID 33784371, 2021). "Peritoneal macrophages from STAT1+/+ and STAT1−/− recruited at 8 weeks post-infection were analyzed for the expression of Arginase-1, Fizz1, and Ym1." (PMID 34684235, 2021). "The sera from STAT1−/− infected mice, obtained 8 weeks post-infection, displayed significantly higher amounts of IL-17A compared to STAT1+/+ mice." (PMID 34684235, 2021). "Co-cultures of PECs from STAT1+/+ mice recruited during infection with T. crassiceps significantly suppressed 3HTDR uptake by total splenocytes." (PMID 34684235, 2021). "We found that in control macrophages STAT1 was robustly phosphorylated at 4- and 6h post-infection, but phospho-STAT1 was undetectable in STING KO or cGAS KO macrophages at all time points." (PMID 34473814, 2021). "Then, cells were harvested after 0 h, 6 h, 12 h and 24 h of infection and the level of the phosphorylated (p) and total (t) STAT1 was detected by western blotting." (PMID 35095845, 2021). "We additionally infected Pou2f3+/-Stat1-/- and Pou2f3-/-Stat1-/- with MNoV strain WU23 containing L514, and found that while lethality was delayed in Pou2f3-/-Stat1-/- mice compared to Pou2f3+/-Stat1-/- littermates, all mice succumbed to infection." (PMID 33705489, 2021). "Consistent with the results of Northern blotting, deep sequencing of total small RNAs revealed production of a typical vsiRNA population by C57BL/6 and Stat1/2−/− mice in response to NoVΔB2 infection." (PMID 32753500, 2020). "In unstimulated luc-transfected cells, infection with T. gondii slightly increased reporter activity, consistent with increased binding of STAT1 to DNA in infected cells, and possibly depending on ROP16 as reported for type I parasites." (PMID 33072127, 2020). "All Cd300lf+/+Stat1-/- and Cd300lf+/-Stat1-/- mice challenged with 106 PFU PO MNoVCR6 survived the seven-day infection." (PMID 32251490, 2020). "We further compared NoV, NoVΔB2, and NoVmB2 infection in STAT1 and STAT2 double-knockout mice (Stat1/2−/−), which are defective in the signaling by type I, II, and III interferons." (PMID 32753500, 2020). "We previously showed that while wildtype (WT) mice develop mild disease and survive infection with lymphocytic choriomeningitis virus (LCMV), LCMV infection of STAT1-deficient mice results in a lethal wasting disease that is dependent on IFN-I and CD4+ cells." (PMID 32310998, 2020). "An easy-accessed model of hybrid hSCARB2+/+/stat-1–/– mice was used for EV-A71 infection and pathogenesis." (PMID 33117346, 2020). "This is in concordance with previous studies on SARS-CoV that although orf3b, orf6 and nucleoprotein of SARS-CoV can individually function as interferon antagonist, infection with orf6-null SARS-CoV triggered STAT1 nuclear translocation." (PMID 32529952, 2020). "According to Hong’s group, a decrease in STAT1 is necessary for the amplification of the viral genome in the early stage of infection, perhaps owing to its ability to suppress interferon-inducible genes, thus evading the immune system." (PMID 33076315, 2020). "We have previously established that following infection with LCMV, STAT1-deficient mice develop a lethal, immunopathological disease." (PMID 32310998, 2020). "In spite of forming homodimers or heterodimers and translocating to the nucleus where they regulated the transcription of target genes, STAT3 and STAT1 played different even in part opposite roles in the process of pathogen infection." (PMID 32878239, 2020). "In stark contrast, the knockout of adapter molecule TRIF strongly reduced ISG induction and STAT1 Tyr701 phosphorylation upon infection with C. acnes or L.m.." (PMID 33178195, 2020). "There was a significant decrease of pDCs in STAT1/RAG1 DKO mice following infection, the numbers similar to that in infected STAT1 KO mice." (PMID 32310998, 2020).
infection (continued). "Compared with the wild type and rFCV F9 infection groups, rFCV F9-2280 p30 infection contributed to a greater reduction in the IFN-induced STAT1 and STAT2 phosphorylation." (PMID 33075108, 2020). "The Irf1 and Stat1 contribute to the control of T. gondii by regulating the expression of factors essential for the host to resist infection, such as Socs1, Ciita, and NOS2." (PMID 33193165, 2020). "Compared with the wild type and rFCV 2280 infection groups, infection with rFCV 2280 F9-p30 led to less of a reduction in the IFN-induced STAT1 and STAT2 phosphorylation." (PMID 33075108, 2020). "Infection of STAT1 KO mice and STAT1 conditional KO mice using an IFN-γ producing strain of C. neoformans resulted in increased fungal burden, increased M2 activation, and reduced anti-cryptococcal activity compared to WT mice." (PMID 32117810, 2020). "Infection of dendritic cells showed a STAT1- and NF-κB-dependent inhibition of proinflammatory cytokine release compared to infection with a PLY-deficient mutant." (PMID 32714314, 2020). "RT-qPCR analysis revealed that the IFN-β gene, RIG-I, and ISG15 were all induced by infection with both NoV and NoVΔB2 in C57BL/6 and Rag1−/− mice compared to that with the infection of Stat1/2−/− mice." (PMID 32753500, 2020). "To investigate the mechanism by which FCV 2280 infection blocks the function of IFN, we first examined the effect of FCV 2280 infection on STAT1 and STAT2 phosphorylation." (PMID 33075108, 2020). "In our experiments, MOPV infection of STAT-1-/- mice induced manifested disease that met euthanasia criteria 11–17 days post-infection." (PMID 30650607, 2019). "We transduced A549 cells with VSV-G-pseudotyped single-round reporter viruses (hereinafter HIV-Luc) and assayed for STAT1 phosphorylation 1 day after infection." (PMID 30755516, 2019). "In contrast to MOPV, ML29 infection in STAT-1-/- mice was more attenuated, and 33% of animals survived in this group." (PMID 30650607, 2019). "The phosphorylated and un-phosphorylated STAT3 competed with STAT1 for binding to the decreased KPNA1 post infection and repressed downstream ISG expression." (PMID 31575039, 2019). "Collectively, these data suggest that IFN-γ indeed has anti-SFTSV activity in vivo when used prophylactically, whereas the antiviral activity can be neutralized after SFTSV infection establishment due to the viral antagonism of IFN-γ-STAT1 signaling." (PMID 31191546, 2019). "In TGEV-infected cells, p-STAT1 at the late stage of infection (24–48 h) accumulated in large amounts near the cell membrane and only a few nuclear translocations occurred." (PMID 31781061, 2019). "Histological examination of the lungs revealed peribronchial and perivascular inflammation during acute infection (4–7 dpi) that healed as the infection progressed in both WT and STAT1−/− mice." (PMID 31810203, 2019). "One of these mutants, VSV-∆M51-GFP31, caused a readily measurable response upon infection of HAP1 wild type cells, as shown by phosphorylation of IRF3 and STAT1 transcription factors." (PMID 31320712, 2019). "Enumeration of lymphocytes, macrophages and polymorphonuclear (PMN) cells revealed greater numbers of macrophages in lung tissue from day 4 to 21 post infection in WT, STAT1−/− and STAT6−/− mice." (PMID 31810203, 2019). "Western blotting of whole-cell lysates from organoids confirmed that the main mediator of IFN-β signaling, the transcription factor STAT1, was strongly phosphorylated upon Ctr infection at levels comparable to that induced by stimulation with exogenous IFN-β." (PMID 30886143, 2019). "We observed that STAT1 was required for the increased accessibility upon infection of up to 60% of the regions that composed cluster I (i.e., the distal regions that are already more active in monocytes from the BM)." (PMID 31872076, 2019). "Using qPCR, we show that STAT1 mRNA expression increased at day 3 and was maximal in WT mice at day 7 post-infection." (PMID 31539400, 2019).
infection (continued). "In MOPV-infected wild-type mice, IL-6 mRNA levels had similar kinetics with those in STAT-1-/- mice, with downregulation in the liver and spleen tissues during the infection." (PMID 30650607, 2019). "Stat1-/- mice exhibit a profound inability to control systemic replication and succumb to infection in a VP1CW3-dependent manner." (PMID 31329638, 2019). "We found that OAdmCherry infection induced type I IFN response as shown by the increase in STAT1 phosphorylation compared to uninfected control and AdGFP infected in MCF7/pS cells but not in MCF7/pR cells." (PMID 31100952, 2019). "At the same time, the amount of p-STAT1 correlated positively with the duration of infection after Lp-1s-treatment of IPEC-J2 cells infected with TGEV." (PMID 31781061, 2019). "During early infection, L. major-infected DCs exhibited a distinct type-I IFN-associated transcriptomic signature, including the upregulation of IRF2, IRF9, STAT1/2, and IFNAR." (PMID 31608064, 2019). "On the other hand, both un-phosphorylated and phosphorylated STAT3 competed with STAT1 for KPNA1 binding upon infection, leading to repressed ISG expressions." (PMID 31575039, 2019). "Immunofluorescence double-staining was also used to determine the infection status of cells expressing STAT1, STAT2 and MX." (PMID 30939763, 2019). "When we knocked down STAT3 with specific siRNAs, the restricted nuclear translocation of activated STAT1 was largely relieved post infection, leading to a recovered antiviral response by the downstream ISGs." (PMID 31575039, 2019). "In contrast, the induction of fecal Lcn-2 observed in MNV-infected Stat1-/- mice at three days post-infection was significantly diminished in both Stat1-/-Nlrp3-/- and Stat1-/-Gsdmd-/- mice." (PMID 31017981, 2019). "The expression of the transcription factor STAT1 also declined over time, but it remained significantly elevated above control 2 months after infection." (PMID 31266862, 2019). "Recently, it has been suggested that, during the chronic stages of infection, IFNs, via STAT1, can have a predominantly suppressive role, inducing pathways involving IL-10 and programmed cell death ligand 1 (PDL1)." (PMID 30235866, 2018). "After infection, the proportion of F4/80+Ly6G- macrophages was unchanged in WT and Ifnar-/- mice but slightly reduced in Stat1-/- mice." (PMID 29668683, 2018). "In the ZIKV-infected Stat1-/- mice (4×104 pfu/mouse), viremia peaked at 2 days post-infection (p = 0.0095), and declined in blood over time." (PMID 29668683, 2018). "Capture-4Tran results are consistent with a model in which a subset of MER41 elements act as interferon-inducible enhancers that contribute to STAT1-mediated transcriptional activation of interferon sensitive genes in response to pathogen infection." (PMID 30541598, 2018). "Enterovirus 71 (EV71) infection suppresses IFN responses by inhibiting STAT1/2 nuclear transport through the induction of caspase-3-dependent degradation of KPNA1." (PMID 29370303, 2018). "Serum NS1 expression in ZIKV-infected Stat1-/- mice gradually increased, suggesting that systemic infection in various tissues, including the brain, continued." (PMID 29668683, 2018). "The transcription factor signal transducer and activator of transcription 1 (STAT1) governs ILC2 expansion during A2001/2-20 infection." (PMID 30513770, 2018). "In fact, EBV was the first virus reported to induce serine monophosphorylation of STAT1 during infection, and serine monophosphorylated STAT1 is able to bind DNA in EBV-infected cells." (PMID 29662014, 2018). "To assess the effect of LY6E expression on uncoating, we incubated STAT1-/- fibroblasts with 25 MOI IAV at 4 °C to synchronize infection." (PMID 30190477, 2018). "Addition of 5 nM bafA as early as 30 min after synchronized infection resulted in a greater percentage of Venus-positive cells in LY6E-expressing STAT1-/- fibroblast populations than in control fluc-expressing populations." (PMID 30190477, 2018).